DDX1 (DEAD-box helicase 1)
Description:
Acts as an ATP-dependent RNA helicase, able to unwind both RNA-RNA and RNA-DNA duplexes. Possesses 5' single-stranded RNA overhang nuclease activity. Possesses ATPase activity on various RNA, but not DNA polynucleotides. May play a role in RNA clearance at DNA double-strand breaks (DSBs), thereby facilitating the template-guided repair of transcriptionally active regions of the genome. Together with RELA, acts as a coactivator to enhance NF-kappa-B-mediated transcriptional activation. Acts as a positive transcriptional regulator of cyclin CCND2 expression. Binds to the cyclin CCND2 promoter region. Associates with chromatin at the NF-kappa-B promoter region via association with RELA. Binds to poly(A) RNA. May be involved in 3'-end cleavage and polyadenylation of pre-mRNAs. It is also an accessory subunit of the tRNA-splicing ligase complex that acts by directly joining spliced tRNA halves to mature-sized tRNAs by incorporating the precursor-derived splice junction phosphate into the mature tRNA as a canonical 3',5'-phosphodiester. Cooperates with ZBTB8OS (also known as archease) for the guanylylation of RTCB, a key intermediate step in activation of the tRNA ligase. Component of a multi-helicase-TICAM1 complex that acts as a cytoplasmic sensor of viral double-stranded RNA (dsRNA) and plays a role in the activation of a cascade of antiviral responses including the induction of pro-inflammatory cytokines via the adapter molecule TICAM1. Specifically binds (via helicase ATP-binding domain) on both short and long poly(I:C) dsRNA (By similarity). (Microbial infection) Required for HIV-1 Rev function as well as for HIV-1 and coronavirus IBV replication. Binds to the RRE sequence of HIV-1 mRNAs. (Microbial infection) Required for Coronavirus IBV replication.
Synonyms: DBP-RB; TSLIG6; UKVH5d
Tractability: Small molecule: a structure with a bound ligand is known. PROTAC: UniProt records ubiquitination sites on it; ubiquitination databases record sites on it; its protein half-life has been measured; a small molecule that binds it is known.
Target class: Enzyme
Gene: Protein-coding gene on chromosome 2 (15,591,178 to 15,634,346, forward strand). Ensembl gene ENSG00000079785.
Subcellular location: Nucleus; Cytoplasm; Cytoplasmic granule; Cytoplasm, cytosol; Mitochondrion
Subcellular location (Human Protein Atlas): Nucleoplasm; Cytosol
Pathways (Reactome):
Metabolism of RNA: tRNA processing in the nucleus
Gene Ontology:
Molecular function: ATP hydrolysis activity; chromatin binding; DNA/RNA helicase activity; nuclease activity; poly(A) binding; protein binding; RNA binding; RNA helicase activity; transcription coregulator activity; ATP binding; double-stranded RNA binding; nucleic acid binding
Biological process: double-strand break repair; protein localization to cytoplasmic stress granule; tRNA splicing, via endonucleolytic cleavage and ligation; positive regulation of canonical NF-kappaB signal transduction; regulation of translational initiation; spliceosomal complex assembly; positive regulation of myeloid dendritic cell cytokine production
Cellular component: cleavage body; cytoplasm; cytoplasmic stress granule; cytosol; membrane; nucleoplasm; nucleus; ribonucleoprotein complex; tRNA-splicing ligase complex; mitochondrion
Genetic constraint (gnomAD): Loss-of-function variants: 8 observed, 43.77 expected, observed/expected ratio (o/e) 0.18, 90% interval 0.11 to 0.33. The upper end of that interval is the gene's LOEUF score, 0.33, which puts it in group 1 of 6, group 1 being the genes least tolerant of losing a copy. Missense variants: 383 observed, 457.88 expected, observed/expected ratio (o/e) 0.84, 90% interval 0.77 to 0.91. Synonymous variants: 162 observed, 157.07 expected, observed/expected ratio (o/e) 1.03, 90% interval 0.91 to 1.17.
Homologues: Orthologues: chimpanzee DDX1 (99% identical), macaque DDX1 (99% identical), rabbit DDX1 (98% identical), dog DDX1 (98% identical), rat Ddx1 (98% identical), mouse Ddx1 (98% identical), pig DDX1 (96% identical), tropical clawed frog ddx1 (90% identical), zebrafish ddx1 (85% identical), Drosophila melanogaster Ddx1 (59% identical), Caenorhabditis elegans Y55F3BR.1 (47% identical). Paralogues in human: DDX17 (19% identical), DDX43 (19% identical), DDX5 (19% identical), DDX54 (19% identical), DDX21 (18% identical), DDX42 (18% identical), DDX41 (18% identical), DDX3Y (18% identical), DDX50 (18% identical), DDX24 (18% identical), DDX3X (18% identical), DDX4 (17% identical), and 26 more.
Diseases named in the same sentence as DDX1 in open-access papers:
DDX1 is named in the same sentence as 37 diseases in open-access papers, as found by Europe PMC text mining. Sharing a sentence is not in itself a finding about the gene and the disease. The quoted sentences say what the papers report.
neuroblastoma (12 papers, 2007 to 2026). Neuroblastoma (NB) is the most common solid, extracranial childhood tumor. "Next, we measured metabolites in neuroblastoma cells ectopically expressing DDX1 compared with cells expressing the truncated DDX1 Δ269-295aa variant or cells expressing physiologic levels of DDX1 using gas chromatography–mass spectrometry (GC-MS)." (PMID 38197697, 2024). "Another NCRR-binding complex consisting of the RNA helicase DDX1 and the cleavage stimulation factor CtsF was isolated from a JCPyV-susceptible neuroblastoma cell line." (PMID 32987952, 2020). "To understand the mechanism of DDX1-induced mTORC1 dependency, we analyzed previously published neuroblastoma gene-expression data from 709 patients." (PMID 38197697, 2024). "In turn, shRNA-mediated DDX1 knockdown in DDX1-MYCN coamplified neuroblastoma cells resulted in reduced phosphorylation of mTOR and P70-S6K." (PMID 38197697, 2024). "To explore the association between mTORC1 pathway activation and the DDX1:DLST interaction, we ectopically overexpressed DDX1 or DDX1 Δ269-295aa in MYCN-amplified neuroblastoma cells." (PMID 38197697, 2024). "Concomitant amplification or copy number gain of two genes is a common phenomenon in cancers, such as MYCN and DDX1 in neuroblastoma, ERBB2/HER2 and TOPOIIα in prostate cancer." (PMID 34461927, 2021). "While DDX1 overexpression induces both early and late viral gene expression, its knockdown suppresses JCPyV infection in the permissive neuroblastoma cell line." (PMID 32987952, 2020). "Although DDX1 did not influence the tumorigenic properties of neuroblastoma cells, ectopic DDX1 expression was associated with significantly reduced neuroblastoma cell size." (PMID 38197697, 2024). "Furthermore, phosphorylation of mTOR at Ser2448 and P70-S6K at Thr389, signs of mTORC1 pathway activation, increased in neuroblastoma cells after ectopic DDX1 expression." (PMID 38197697, 2024). "Even though rapamycin is only one of four agents used in this treatment protocol, it will be important to test whether neuroblastoma patients with DDX1-MYCN amplifications respond better to RIST than neuroblastoma patients without such coamplifications." (PMID 38197697, 2024). "DDX1 is specifically expressed in neuroblastoma cells and binds directly to the JCPyV NCRR." (PMID 32987952, 2020). "To verify the role of DDX1 as a passenger in the pathogenesis of neuroblastoma in an in vivo experimental system, we generated a transgenic zebrafish line that stably expresses human DDX1 in the peripheral sympathetic nervous system and compared those to zebrafish expressing both DDX1 and MYCN." (PMID 38197697, 2024). "Indeed, incubation of neuroblastoma cell lines in the presence of membrane-permeable Dimethyl 2-oxoglutarate (DM-KG) was accompanied by mTORC1 pathway activation, phenocopying the effects of DDX1 overexpression." (PMID 38197697, 2024). "DEAD-box helicase 1(DDX1), a member of the DEAD-box RNA helicases family, and was first discovered in retinoblastoma and neuroblastoma in 1993." (PMID 33472667, 2021). "Only the neuroblastoma-amplified gene (NAG), DEAD (Asp-Glu-Ala-Asp) box polypeptide 1 (DDX1), MYCN and hypothetical protein LOC81553 (FAM49A) are present in this region between 15.5 × 106 bp and 17.5 × 106 bp from 2pter." (PMID 17601344, 2007). "In line with its role as a passenger gene, short hairpin RNA (shRNA) mediated DDX1 knockdown in DDX1-MYCN coamplified neuroblastoma cell lines did not reduce neuroblastoma proliferation." (PMID 38197697, 2024). "In turn, shRNA-mediated DDX1 knockdown in neuroblastoma cells with a DDX1-MYCN coamplification resulted in reduced rapamycin sensitivity, indicating that high DDX1 expression was required for mTOR inhibitor sensitivity in the context of DDX1-MYCN coamplification." (PMID 38197697, 2024). "NAG and DDX1 are reported to be co-amplified with the MYCN gene in neuroblastoma, but amplification of DDX1 and/or NAG has no additional adverse effect on prognosis in this disease." (PMID 17601344, 2007).
neuroblastoma (continued). "Ectopic expression of DDX1 did not affect viability and neuroblastoma cell proliferation." (PMID 38197697, 2024). "To test whether DDX1 expression was sufficient to induce mTORC1 pathway activation, we analyzed mTORC1 activity by RNA sequencing and immunoblot analyses of MYCN-amplified neuroblastoma cells after ectopic DDX1 expression." (PMID 38197697, 2024). "This suggests that DDX1 is sufficient to drive mTORC1 pathway activation in the context of MYCN amplification without affecting the oncogenic potential of neuroblastoma cells, which could generate the dependency on mTORC1 observed in cancer cells harboring DDX1-MYCN amplifications." (PMID 38197697, 2024). "Consistently, neuroblastoma cell lines harboring DDX1-MYCN coamplification had elevated DDX1 protein and mRNA levels compared with those lacking DDX1 coamplifications or cells without MYCN amplification." (PMID 38197697, 2024). "To further test the effect of high DDX1 expression in cancer cells, we selected human neuroblastoma cell lines harboring MYCN amplifications, not including DDX1 and introduced a doxycycline-inducible DDX1 expression vector." (PMID 38197697, 2024). "Our in-depth investigation of DDX1 coamplification revealed a previously unanticipated and fundamentally new role of DDX1 in cellular metabolism by uncovering its interaction with the α-KGDH complex as a noncanonical interaction partner of the DLST subunit in neuroblastoma cells." (PMID 38197697, 2024).
breast carcinoma (4 papers, 2012 to 2022). "“Here, we identify DDX1 RNA overexpression as an independent prognostic marker for early recurrence in primary breast cancer......”." (PMID 23216862, 2012). "DDX1 has been widely reported to activate the transcription of oncogenes for promoting tumorigenesis in multiple tumours (e.g., testicular tumours, nephroblastoma, breast cancer, and colorectal cancer)." (PMID 36054300, 2022). "Moreover, researchers have found that DDX1 promotes tumorigenesis in various carcinomas, such as retinoblastoma, neuroblastoma, testicular carcinoma, colorectal cancer, and breast cancer." (PMID 36451087, 2022). "Researchers have proved that high DDX1 expression is associated with improvement in local control, distant metastatic-free survival, and OS when compared with low DDX1 expression in node-negative and early-stage patients with breast cancer." (PMID 36451087, 2022).
viral infection (4 papers, 2021 to 2023). "DEAD-box helicase 1 (DDX1) plays a critical role in the innate immune system against viral infection." (PMID 33472667, 2021). "In conclusion, this study identified DExD-Box RNA helicase DDX50 as a crucial component facilitating DDX1-independent IRF3 activation following stimulation with dsRNA or viral infection and further established a pivotal role for DDX50 as a viral restriction factor for RNA and DNA viruses." (PMID 35215908, 2022). "The N protein of SARS-CoV-2 has been found to interact with several RNA helicases, including DDX1, DDX3, DDX5, DDX6, DDX21, and DDX10; among them, DDX1, DDX5, and DDX6 are essential for virus replication, while DDX21 and DDX10 restrict the viral infection." (PMID 38328580, 2023). "In addition, when DDX1 was knocked down by shRNA, the ability of the DF-1 cells to produce IFN-β in response to a viral infection or stimulation with poly(I:C) was significantly reduced." (PMID 34630423, 2021).
Wilms tumor (4 papers, 2013 to 2022). An embryonal neoplasm characterized by the presence of epithelial, mesenchymal, and blastema components. "We cannot therefore rule out a significant role for DDX1 in Wilms tumour." (PMID 25749049, 2015).
ovarian tumor (3 papers, 2018 to 2022). "Ovarian tumours induce miR200 expression upon DNA damage involving another RNA helicase, namely DDX1." (PMID 30539330, 2019). "DDX1 was distributed in RNA-transporting granules in dendrites of neurons as well as in astrocytes, cytoplasm, and nucleus and has also proven to be a key modulator in miRNA maturation and ovarian tumor suppression." (PMID 35493736, 2022). "Indeed, an earlier report found that DDX1 correlated with ovarian tumor metastasis and progression." (PMID 30279964, 2018).
bladder cancer (2 papers, 2022 to 2025). "In bladder cancer, ZBTB11 promotes the transcription of DDX1, an RNA helicase required for R‐loop clearance." (PMID 36054300, 2022).
COVID-19 (2 papers, 2022). A disease caused by infection with severe acute respiratory syndrome coronavirus 2. "Furthermore, DDX1 as a regulatory component of the Drosha microprocessor pathway (WP2942) depicting the posttranscriptional maturation of microRNA is more active with all proteins detected more abundant in COVID-19." (PMID 36189295, 2022). "Interestingly, among these known virus-host PPIs, 13 splicing factors were downregulated in the COVID-19 patients, including three members of RNA helicase, DDX5, DDX17 and DDX1." (PMID 35421082, 2022).
acute myeloid leukemia (1 paper, 2019). Acute myeloid leukemia (AML) is a group of neoplasms arising from precursor cells committed to the myeloid cell-line differentiation. "hnRNP K, a known binding partner of DDX1, was shown to regulate autophagy and was upregulated in acute myeloid leukemia cells derived from non-remission patients." (PMID 31573152, 2019).
Alzheimer disease (1 paper, 2025). A progressive, neurodegenerative disease characterized by loss of function and death of nerve cells in several areas of the brain leading to loss of cognitive function such as memory and language. "Additionally, the TREAT-AD (TaRget Enablement to Accelerate Therapy development for Alzheimer’s Disease) Center has identified MDA5, LGP2, and DDX1 as potential risk factors in Alzheimer’s disease progression." (PMID 39975009, 2025).
chronic kidney disease (1 paper, 2024). Impairment of the renal function secondary to chronic kidney damage persisting for three or more months. "Furthermore, genes that have been implicated in chronic kidney disease (CKD), such as Slc6a6 were up-regulated in ECs, and Umod, Cacna1d, Ddx1 were specifically up-regulated in PTs." (PMID 38641839, 2024).
glioblastoma (1 paper, 2021). The most malignant astrocytic tumor (WHO grade IV). "The non-structural protein 3 (nsp3) of Venezuelan equine encephalitis virus (VEEV) interacts with DDX1 and DDX3 in infected U87MG glioblastoma cells to facilitate viral multiplication of the U87MG glioblastoma cell to promote virus replication." (PMID 34630423, 2021).
hypogammaglobulinemia (1 paper, 2022). "In addition, a de novo frameshift variant in the highly intolerant DDX1 (pLI 0.994) was identified in a patient with hypogammaglobulinemia, hematopoietic cell lineage abnormalities and recurrent infections." (PMID 36250618, 2022).
latent infection (1 paper, 2021). "On the other hand, a dramatic increase in latent infection was seen after knockdown of TOP2A, SRP14, HNRNPH1, DDX1, and HNRNPL (blue bars)." (PMID 34194479, 2021).
melanoma (1 paper, 2019). A malignant, usually aggressive tumor composed of atypical, neoplastic melanocytes. "In the present study, we have identified potential molecular targets of novel spliceosomal probe 2155–14 in melanoma cells – DDX1, hnRNPH2 and hnRNPA2/B1." (PMID 31573152, 2019). "In the present study, we identified ATP-dependent RNA helicase DDX1 and heterogeneous nuclear ribonucleoproteins (hnRNPs) H1, H2 and A2/B1 as targets of anti-melanoma compound 2155–14." (PMID 31573152, 2019). "In the present study, DDX1, hnRNP H2 (and possibly H1), and hnRNP A2/B1 have been identified as targets of an anti-melanoma compound 2155–14." (PMID 31573152, 2019). "Following incubation with 2155–14, DDX1, hnRNP H2, and hnRNP A2/B1 levels decreased in WM266–4 melanoma cells but not HEK293 cells." (PMID 31573152, 2019).
Miscarriage (1 paper, 2014). A pregnancy that ends at a stage in which the fetus is incapable of surviving on its own, defined as the spontaneous loss of a fetus before the 22th week of pregnancy. "It comprised four genes (TRIB2, FAM84A, NBAS (NAG) and DDX1), whose molecular functions did not imply an obvious cellular cause for miscarriage." (PMID 25013457, 2014).
ovarian carcinoma (1 paper, 2015). A malignant neoplasm originating from the surface ovarian epithelium. "Similarly, they reported DDX1, one of the Drosha associated polypeptides, promotes pri-miRNAs maturation in ovarian cancer." (PMID 26308063, 2015). "These miRNAs were reported to be related to a mesenchymal feature in serous ovarian cancer, suggesting that DDX1 might regulate the progression of ovarian cancer." (PMID 26308063, 2015).
SARS-CoV infection (1 paper, 2023). "In the context of SARS-CoV infection, DEAD-box helicase 1 (DDX1) RBP has been shown to facilitate template read-through and thus replication of genomic viral RNA, while heterogeneous nuclear ribonucleoprotein A1 (hnRNPA1) might regulate viral RNA synthesis." (PMID 36814457, 2023).
Stroke (1 paper, 2024). Sudden impairment of blood flow to a part of the brain due to occlusion or rupture of an artery to the brain. "NeuN staining in the peri‐infarct region revealed that circSCMH1 markedly hindered post‐stroke neuronal loss, which was mitigated by DDX1 knockdown." (PMID 39444078, 2024). "DEAD Box 1 (DDX1) bound to circSCMH1 (a circular RNA involved in vascular post‐stroke repair) facilitates the formation of membrane‐associated RNA‐containing vesicles (MARVs) and enhances the activity of astrocytic microdomain Ca2+ transients, thereby promoting behavioral recovery." (PMID 39444078, 2024). "Consistent with the analysis of neuronal loss, EV‐circSCMH1 treatment significantly enhanced the spine numbers in the peri‐infarct cortex of mice at day 4 after stroke, and DDX1 knockdown attenuated the beneficial effects of EV‐circSCMH1 treatment." (PMID 39444078, 2024). "Subsequently, we used the administration of EV‐circSCMH1 to compare astrocytic microdomain Ca2+ transients in control and DDX1 knockdown mice after stroke." (PMID 39444078, 2024). "Our results show that the levels of neuronal Ca2+ transients were significantly decreased in mice with astrocyte‐specific DDX1 knockdown after the administration of EV‐circSCMH1 under stroke conditions." (PMID 39444078, 2024). "The synergy of neuronal function in DDX1‐knockdown mice was also significantly weakened following stroke." (PMID 39444078, 2024). "Likewise, in the adhesive removal test, the DDX1 knockdown mice required more removal time than control mice after stroke." (PMID 39444078, 2024). "By interacting with circSCMH1, DDX1 participated in the formation of MARVs, thereby enhancing the transport of Ca2+ to the mitochondria, and ultimately promoting the generation of microdomain Ca2+ transients after stroke." (PMID 39444078, 2024). "However, astrocyte‐specific downregulation of DDX1 expression inhibited the formation of MARVs, diminished the microdomain Ca2+ transients, and reduced the efficacy of extracellular vesicle (EV) delivery of circSCMH1 in enhancing post‐stroke recovery." (PMID 39444078, 2024).